EGFR (epidermal growth factor receptor)
Diseases named in the same sentence as EGFR in open-access papers (continued):
Sharing a sentence is not in itself a finding about the gene and the disease.
anaplastic oligodendroglioma (7 papers, 2008 to 2024). A WHO grade III oligodendroglioma with focal or diffuse malignant morphologic features (prominent nuclear pleomorphism, mitoses, and increased cellularity). "CHI3L1 expression was higher in GBMs compared to anaplastic oligodendrogliomas, and among GBMs, tumors with EGFR amplification or elevated EGFR expression had lower CHI3L1 expression." (PMID 39033204, 2024). "In French’s dataset, the expression of EGFR was 9.847 times higher in anaplastic oligodendroglioma tissues than in normal tissues." (PMID 33892666, 2021). "In conclusion, the present study shows that combination of EGFR kinase inhibitors with ionizing radiation could be a potent therapeutic strategy to treat anaplastic oligodendrogliomas characterized by EGFR abnormalities." (PMID 23874590, 2013). "We focused on three models of anaplastic oligodendrogliomas (TCG2, TCG3 and TCG4) harboring high levels of phospho-EGFR, phospho-AKT and phospho-MEK1." (PMID 23874590, 2013).
and neck cancer (7 papers, 2012 to 2025). "EGFR often is mutated and/or overexpressed in several types of human cancers, including lung, ovary, breast, head, and neck cancer, and it serves to modulate the growth, differentiation, signaling, adhesion, migration, and survival of cancer cells." (PMID 32204508, 2020). "EGFR inhibitors are approved as the drug for the treatment of non-small cell lung, colorectal, breast, pancreatic, head, and neck cancers with EGFR mutations." (PMID 29577050, 2018).
Autoimmunity (7 papers, 2011 to 2024). The occurrence of an immune reaction against the organism's own cells or tissues. "Why the amphiregulin/EGFR pathway is not effective in supporting beta cell function is unclear, but could point to another reason for the inability of Tregs to effectively control anti-beta cell autoimmunity." (PMID 37903947, 2023). "To determine whether inflammatory signals during T1D modify levels of EGFR expression on beta cells, we measured EGFR levels on beta cells from NOD.scid mice, which lack T and B cells and do not develop autoimmunity." (PMID 37903947, 2023).
bile duct cancer (7 papers, 2014 to 2026). "In bile duct cancers (BDC), EGFR pathway dysregulation is common, with nearly half of tumors showing EGFR overexpression and a few cases harboring EGFR mutations." (PMID 40364160, 2025). "The frequency of EGFR (epidermal growth factor receptor) expression in bile duct carcinomas is different depending on the analysis method." (PMID 38846220, 2024). "Another study revealed that CLDN18 coupled with modulation of epidermal growth factor receptor (EGFR) / extracellular signal-regulated kinase (ERK) signaling contributes to the malignant potential of bile duct cancer." (PMID 35642043, 2022). "Breast, pancreas and bile duct cancer cell line experiments suggested that TFF2 expression induces cell migration via Platelet-Activation Receptor 4 (PAR4) and Panc1 activation, as well as mitosis via EGFR/MAPK axis signaling." (PMID 24555920, 2014).
Cachexia (7 papers, 2012 to 2026). Severe weight loss, wasting of muscle, loss of appetite, and general debility related to a chronic disease. "We evaluated the impact of baseline cachexia on toxicity and clinical outcomes in patients with EGFR-mutated stage III–IV NSCLC treated with EGFR-TKIs." (PMID 41928147, 2026). "Hence, we speculate that the EGFR-ProT-NF-κB-HOTAIR signaling axis contributes to both cisplatin-induced cachexia and tumor growth caused by cisplatin resistance." (PMID 36471329, 2022). "CONCLUSIONS: Baseline cachexia was associated with a higher burden of early hematologic toxicity and independently worse OS in EGFR-mutated advanced NSCLC treated with EGFR-TKIs." (PMID 41928147, 2026). "Lewis lung carcinoma (LLC) cells, which naturally overexpress endogenous EGFR, form tumors at a fast clip and result in cachexia in syngeneic C57BL/6 mice." (PMID 39273055, 2024). "In this study, we used a murine cancer cachexia model to investigate the effects of a nutritional formula (NuF) rich in fish oil and selenium yeast as an adjuvant to enhance the drug efficacy of an EGFR inhibitor (Tarceva)." (PMID 39273055, 2024). "Our study showed that the presence of a KRAS mutation in the tumor correlated with the development of cachexia, whereas EGFR mutation was not significantly correlated with cachexia." (PMID 27485414, 2016).
carcinoid (7 papers, 2013 to 2025). "We report the case of a 71-year-old female in whom three distinct primary lung cancers were identified: carcinoid tumor, adenocarcinoma with KRAS mutation, and adenocarcinoma with EGFR mutation." (PMID 40642683, 2025). "The genomic and pathologic data generated here support predominant adenocarcinoma-to-SCLC plasticity in this subset and its association with EGFR mutations and APOBEC mutagenesis and contrast this pathway with carcinoid-to-SCLC plasticity associated with chromothripsis in aSCLC." (PMID 39185963, 2025). "No EGFR or KRAS driver mutations were found in carcinoid histology, whereas an enrichment was found for driver mutations in ARID1A." (PMID 38798417, 2024). "Acting as EMT transcription factors, EGFR and STEAP1 were proved to be highly expressed among pulmonary neuroendocrine carcinomas and downregulated in carcinoid tumors, which suggested that STEAP1 may have interaction with EGFR pathway in the process of EMT." (PMID 35313641, 2022).
colon adenoma (7 papers, 2011 to 2023). An adenoma that arises from the colon. "We used a peptide to visualize EGFR expression in colonic adenomas because of their small size and low molecular weight by comparison to antibodies." (PMID 27874037, 2016). "The Apcmin/+ mouse is of particular relevance as we show that harvested colon adenomas are wild type for K-ras and therefore relevant for the study of EGFR-targeted therapy and resistance." (PMID 21811251, 2011). "The acute increased IGF1R activity in colon adenomas following exposure to EGFR blockade raises the possibility of testing tumour specimens or circulating tumour cells for their initial response to drug." (PMID 21811251, 2011). "Four hours following exposure to 75 mg kg−1 gefitinib we observed reduced levels of phosphorylated EGFR in colon adenomas and suppressed downstream phosphorylation of ERK and AKT." (PMID 21811251, 2011).
diarrhoea (7 papers, 2014 to 2026). "Diarrhoea was another AE found to be associated with the use of BTK inhibitors, which is also often related to inhibition of the EGFR." (PMID 36438789, 2022). "Diarrhoea is one of the most common adverse events recorded following treatment with all TKIs and is a dose limiting toxicity for TKIs that block EGFR signalling." (PMID 25126444, 2014). "However, the risk of grade 1–5 diarrhea and rash significantly increased in adjuvant EGFR-TKIs group (Diarrhea: RR 3.17, 95% CI 2.71–3.71; Rash: RR 4.12, 95% CI 3.51–4.84)." (PMID 35346117, 2022). "However, the pooled RRs of grade 3–5 diarrhea and rash incidence were significant for the adjuvant EGFR-TKIs group (Diarrhea: RR 5.68, 95% CI 2.94–10.98; Rash: RR 27.74, 95% CI 11.43–67.30)." (PMID 35346117, 2022). "However, our group has recently developed the first rat model of EGFR TKI-induced diarrhoea." (PMID 25126444, 2014).
ductal carcinoma in situ (7 papers, 2011 to 2024). "This is supportive of recently published data which show an additive effect of EGFR/Notch inhibition on CSC activity in primary human ductal carcinoma in situ." (PMID 23497505, 2013).
gastritis (7 papers, 2017 to 2023). Inflammation of the stomach. "Chronic atrophic gastritis rats may participate in gastric mucosal barrier injury, cell proliferation, and apoptosis by regulating the expression of EGFR and Wei-Wei-Kang-Granule against gastritis by decreasing the express of EGFR in gastric mucosa." (PMID 34471638, 2021). "Therefore, we inferred that Weibing Formula 1 might be involved in the progression of gastritis by regulating EGFR activation MAPK signaling pathway and cytokine-cytokine receptor interaction pathway." (PMID 34471638, 2021). "In addition, PTGS2, TRL4, MMP9, JAK1, EGFR, CYP2C19, and PTGS1 were identified as crucial anti-gastritis target genes in C. cassia." (PMID 35336597, 2022). "PTGS2, NOS2, EGFR, MMP9, CXCL2, CXCL8, and IL-10 may be the important direct targets of Weibing Formula 1 in gastritis treatment." (PMID 34471638, 2021). "In conclusion, the potential mechanism of Weibing Formula 1 in treating gastritis has the multicomponent, multitarget, and multiway characteristics, and PTGS2, NOS2, EGFR, MMP9, CXCL2, CXCL8, and IL-10 may be the important direct targets of Weibing Formula 1 in gastritis treatment." (PMID 34471638, 2021).
Glucose intolerance (7 papers, 2014 to 2025). Glucose intolerance (GI) can be defined as dysglycemia that comprises both prediabetes and diabetes. "Upon EGFR deletion, the effect of Exendin-4 on β-cell and islet size, β-cell proliferation, and insulin content is decreased, causing development of glucose intolerance and supporting the cross-talk between Exendin-4/GLP-1 and EGFR." (PMID 39966897, 2025). "Additionally, inhibiting EGFR improved HFD-induced glucose intolerance." (PMID 30735525, 2019).
Hepatitis (7 papers, 2011 to 2025). Inflammation of the liver. "We discuss the challenges in treatment selection due to the patient’s compound de novo EGFR mutations, management of her osimertinib-induced hepatitis, and the successful re-introduction of osimertinib following the failure of alternative therapies." (PMID 40700234, 2025). "Following discontinuation of an EGFR-TKI due to hepatitis, the benefits and risks of other EGFR-TKI treatments should be considered." (PMID 22188652, 2011). "Meanwhile, we observed that in hepatitis-related HCC, patients with higher expression of BCL2L1, EGFR, ESR1, HNF4A, MAPK8, and PTEN, and lower expression of HDAC1 had a better clinical prognosis." (PMID 36133813, 2022). "Although CHM is associated with drug-induced hepatitis, analysis in the current study showed that incidence of hepatic dysfunction was not enhanced by adding CHM to EGFR-TKIs." (PMID 34512332, 2021). "However, the incidences of treatment-related hepatitis and bleeding were higher, although not significantly, in the EGFR-TKI plus bevacizumab group than in the EGFR-TKI plus ramucirumab group (19.1% vs. 6.1%, p = 0.055; 8.5% vs. 2.1%, p = 0.156; respectively)." (PMID 36765600, 2023).
Hypercholesterolemia (7 papers, 2014 to 2023). An increased concentration of cholesterol in the blood. "Inhibition by modulation of EGFR provides new insights into the development of drugs for the treatment of hypercholesterolemia." (PMID 35978819, 2022). "The hypercholesterolemia in the knockout mice is apparently a result of increased EGFR activation, as inhibition of EGFR with TKI reduces hypercholesterolemia." (PMID 34206547, 2021). "EGFR activation in the Mig-6 deletion mice downregulated CYP7A1 protein expression resulting in hypercholesterolemia." (PMID 28053990, 2016). "In this study, we investigated the effects of EGFR inhibition to identify a potential new treatment target for hypercholesterolemia." (PMID 25486251, 2014). "Moreover, EGFR inhibition is shown to be useful for the treatment of hypercholesterolemia in high-fat-diet-fed Mitogen-inducible gene 6 (Mig-6) Mig-6d/d mice." (PMID 35844366, 2022). "The serum chemistry profiles suggest that EGFR signaling is responsible for lipid metabolism, and EGFR tyrosine kinase inhibitors may improve the hypercholesterolemia induced by dysregulated EGFR signaling." (PMID 25486251, 2014). "By this study, we demonstrated a novel relationship between EGFR and hypercholesterolemia and provided new insight into possible treatment targets for hypercholesterolemia via modulation of EGFR inhibition, the mechanism of action of which differs from that of statins." (PMID 25486251, 2014). "Taken together, these results suggest that EGFR inhibition is effective for the treatment of hypercholesterolemia in high-fat-diet-fed Mig-6d/d mice, and our findings provide new insights into the development of possible treatment targets for hypercholesterolemia via modulation of EGFR inhibition." (PMID 25486251, 2014). "Finally, further studies are needed to investigate EGFR signaling dysregulation in patients with hypercholesterolemia who do not respond to statins." (PMID 25486251, 2014). "However, the roles of EGFR and EGFR kinase inhibitors in hypercholesterolemia have not been studied systematically." (PMID 25486251, 2014).
Hyperkeratosis (7 papers, 2014 to 2025). Hyperkeratosis is a histopathological term defining a thickened stratum corneum and may be present in many different skin conditions, with many possible overlaps. "We first generated EGFR-silenced HaCaT cells with two siRNAs to examine the influence of EGFR on hyper-keratosis." (PMID 32296111, 2020). "The comparable hyperkeratosis rates observed with both TKIs imply a class effect potentially mediated through EGFR or PDGFR pathway inhibition, which may disrupt keratinocyte proliferation and differentiation homeostasis." (PMID 40642018, 2025). "Several reports have suggested that the formation of an abnormal pilosebaceous unit, hyperkeratosis, and keratin cysts in mice may be ascribed to the activation of EGFR signaling and the Nrf2-induced upregulation of Epgn." (PMID 37760426, 2023). "However, it might be reasonable to observe modifications in the epithelial lining features such as keratosis, hyperkeratosis, atrophy or basal cell degeneration; or from the inflammatory infiltrate such as the intensity, cellular types and pattern with different EGFR expression intensity." (PMID 24880441, 2014). "Taken together, all these results confirmed that JNK2, upon being phosphorylated by s-HBEGF-activated EGFR, could stabilize SIRT1 and give rise to hyper-keratosis." (PMID 32296111, 2020).
keloid (7 papers, 2017 to 2024). An irregularly shaped, elevated mark on the skin caused by deposits of excessive amounts of collagen during wound healing. "The authors concluded that CAP can therefore have beneficial therapeutic effects on the pathogenesis of keloid scars and on normal wound healing, which are mediated by the EGFR/STAT3 signaling pathway." (PMID 34829774, 2021). "NTP can therefore have beneficial therapeutic effects mediated by the EGFR/STAT3 signalling pathway on the pathogenesis of keloid scars and on normal wound healing." (PMID 29145520, 2017). "•CCNB1, EGFR, E2F8, BTG1, TP63, and IGF1 were associated with keloids." (PMID 39157347, 2024). "It has been reported that EGFR is down-regulated in keloid tissues, consistent with our results." (PMID 39157347, 2024). "Significantly decreased expressions of TGF-β1, EGFR, Smad 2/3 complex, and Erk 1/2 protein were observed in mortalin specific shRNA-expressing adenovirus treated keloid spheroids, by 52%, 43%, 11%, and 42%, respectively, versus scramble virus-transduced spheroids (*p < 0.05, **p < 0.01)." (PMID 29021584, 2017). "Although keloid pathophysiology is still unclear, there are several molecular mechanisms known to be involved, including signalling regulated by growth factors such as epidermal growth factor receptor (EGFR) and vascular endothelial growth factor." (PMID 29145520, 2017). "Therefore, the down-regulation of EGFR may promote the development of keloids." (PMID 39157347, 2024). "A fibroblast-related diagnostic model for keloid based on a six-gene signature (CCNB1, EGFR, E2F8, BTG1, TP63, and IGF1) was proposed, showing high predictive accuracy in keloid diagnosis." (PMID 39157347, 2024). "In the training dataset, the expression levels of CCNB1, EGFR, E2F8, BTG1, as well as TP63 were remarkedly lower in the keloid samples than in the control samples (P < 0.05); however, the expression of IGF1 was evidently enhanced in the keloid samples elative to the control samples (P < 0.05)." (PMID 39157347, 2024). "The established model based on CCNB1, EGFR, E2F8, BTG1, TP63, and IGF1 showed good performance and may be useful for keloid diagnosis." (PMID 39157347, 2024). "Inhibition of EGFR/STAT3 pathway by NTP may be a useful therapeutic and preventive strategy for keloid therapy." (PMID 29145520, 2017). "After the transduction of dE1-RGD/GFP/shMot, expressions of the major ECM components are significantly decreased in primary keloid spheroid, and knockdown of mortain can attenuate EGF/EGFR signaling pathway and TGF-β1/Smad pathway, which have a role in the fibrogenesis." (PMID 29021584, 2017). "In comparison to levels in control tissues, the expression levels of CCNB1, EGFR, BTG1, as well as TP63 were evidently lower in the keloid tissues (P < 0.05), while the expression levels of E2F8 as well as IGF1 were evidently higher in the keloid tissues (P < 0.05)." (PMID 39157347, 2024).
lupus nephritis (7 papers, 2022 to 2025). Glomerulonephritis in the context of systemic lupus erythematosus. "TNF-α and HB-EGF, both ADAM17 substrate, are associated with renal damage in lupus nephritis by activation of the EGFR signal pathway and by causing renal inflammation, indicating a role for EGFR ligands or EGFR in the pathogenesis of renal fibrous formation." (PMID 40224489, 2025). "Activated EGFR upregulates ROS production and endoplasmic reticulum stress, and this mechanism plays an important role in the pathogenesis of lupus nephritis." (PMID 36304300, 2022). "Furthermore, RHBDF2 activates tumor necrosis factor (TNF)‐α, and epidermal growth factor receptor (EGFR) signaling and enhances lupus nephritis." (PMID 36943228, 2023). "In addition, EGFR pathway activation is essential for the development of kidney fibrosis, which serves as a marker of renal prognosis and also a predictor of treatment response in lupus nephritis, one of the most severe symptoms of SLE." (PMID 39918986, 2025).
mantle cell lymphoma (7 papers, 2015 to 2024). Mantle cell lymphoma is a rare form of malignant non-Hodgkin lymphoma affecting B lymphocytes in the lymph nodes in a region called the ``mantle zone''. "Pre-clinical models of mantle cell lymphoma (MCL) and EGFR mutation-positive non-small cell lung cancer (NSCLC) demonstrate collaborative innate-adaptive anti-tumor immune responses both in vitro and in vivo." (PMID 37194236, 2023). "Ibrutinib, a clinically approved irreversible BTK kinase inhibitor for Mantle Cell Lymphoma (MCL) and Chronic Lymphocytic Leukemia (CLL) etc, has been reported to be potent against EGFR mutant kinase and currently being evaluated in clinic for Non Small Cell Lung Cancer (NSCLC)." (PMID 27626175, 2016).
myopia (7 papers, 2016 to 2025). "Cell migration, particularly in the sclera, is critical for myopia progression, with EGFR signaling playing a significant role in this process." (PMID 40110040, 2025). "Mechanistically, amphiregulin may promote myopia progression by activating the EGFR–ERK–mTORC1 signaling pathway." (PMID 40990868, 2025). "Mutations in this gene are associated with nonsyndromic severe myopia and cataract.AP2M1 (adaptor-related protein complex 2, mu 1 subunit, Gene ID: 1173) gene is also involved in several biological processes and participates in the epidermal growth factor receptor (EGFR) signaling pathway." (PMID 27007896, 2016).